SHOC2 (SHOC2 leucine rich repeat scaffold protein)
Description:
Core component of the SHOC2-MRAS-PP1c (SMP) holophosphatase complex that regulates activation of the MAPK pathway. Acts as a scaffolding protein in the SMP complex. The SMP complex specifically dephosphorylates the inhibitory phosphorylation at 'Ser-259' of RAF1 kinase, 'Ser-365' of BRAF kinase and 'Ser-214' of ARAF kinase, stimulating their kinase activities. The SMP complex enhances the dephosphorylation activity and substrate specificity of PP1c. Acts as an inhibitor of keratinocyte differentiation via interaction with RAS protein complexes that promote ERK activation.
Synonyms: KIAA0862; SOC2; SUR-8; SOC-2; SUR8; NSLH1; SIAA0862
Tractability: Small molecule: a structure with a bound ligand is known. PROTAC: ubiquitination databases record sites on it; its protein half-life has been measured.
Gene: Protein-coding gene on chromosome 10 (110,917,932 to 111,017,307, forward strand). Ensembl gene ENSG00000108061.
Subcellular location: Cytoplasm; Nucleus
Subcellular location (Human Protein Atlas): Cytosol; Nucleoplasm
Pathways (Reactome):
Disease: Gain-of-function MRAS complexes activate RAF signaling; SHOC2 M1731 mutant abolishes MRAS complex function
Signal Transduction: RAF activation
Gene Ontology:
Molecular function: protein binding; protein phosphatase 1 binding; protein phosphatase binding; protein phosphatase regulator activity
Biological process: negative regulation of keratinocyte differentiation; positive regulation of Ras protein signal transduction; regulation of MAPK cascade; cyclic-GMP-AMP transmembrane import across plasma membrane; fibroblast growth factor receptor signaling pathway; intracellular signal transduction; nerve growth factor signaling pathway; cellular response to growth hormone stimulus; negative regulation of neural precursor cell proliferation; negative regulation of neuron differentiation; positive regulation of neuron differentiation; positive regulation of neuron projection development
Cellular component: cytoplasm; cytosol; nucleus; protein phosphatase type 1 complex
Genetic constraint (gnomAD): Loss-of-function variants: 2 observed, 31.34 expected, observed/expected ratio (o/e) 0.0638, 90% interval 0.025 to 0.2. The upper end of that interval is the gene's LOEUF score, 0.2, which puts it in group 1 of 6, group 1 being the genes least tolerant of losing a copy. Missense variants: 297 observed, 537.79 expected, observed/expected ratio (o/e) 0.55, 90% interval 0.5 to 0.61. Synonymous variants: 164 observed, 195.68 expected, observed/expected ratio (o/e) 0.84, 90% interval 0.74 to 0.95.
Gene-disease validity (ClinGen):
ClinGen rates the evidence that SHOC2 causes each of these diseases.
Noonan syndrome-like disorder with loose anagen hair (autosomal dominant): Definitive.
cardiofaciocutaneous syndrome (autosomal dominant): Disputed. Cardiofaciocutaneous (CFC) syndrome is a RASopathy characterized by craniofacial dysmorphology, congenital heart disease, dermatological abnormalities (most commonly hyperkeratotic skin and sparse, curly hair), growth retardation and intellectual disability.
Costello syndrome (autosomal dominant): Disputed. Costello syndrome (CS) is a rare multisystemic disorder characterized by failure to thrive, short stature, developmental delay or intellectual disability, joint laxity, soft skin, and distinctive facial features.
Noonan syndrome (autosomal dominant): Disputed. Noonan Syndrome (NS) is characterized by short stature, typical facial dysmorphism and congenital heart defects.
Homologues: Orthologues: chimpanzee SHOC2 (100% identical), pig SHOC2 (100% identical), dog SHOC2 (99% identical), rabbit SHOC2 (99% identical), macaque SHOC2 (99% identical), mouse Shoc2 (98% identical), rat Shoc2 (98% identical), guinea pig SHOC2 (97% identical), tropical clawed frog shoc2 (91% identical), zebrafish shoc2 (88% identical). Paralogues in human: SCRIB (29% identical), ERBIN (25% identical), LRRC7 (25% identical), PHLPP1 (25% identical), PHLPP2 (24% identical), LRRC40 (24% identical), LRRC1 (23% identical), LRRD1 (23% identical), LRRIQ4 (22% identical), MFHAS1 (21% identical), PIDD1 (20% identical), LRRC8A (18% identical), and 19 more.
Diseases named in the same sentence as SHOC2 in open-access papers:
SHOC2 is named in the same sentence as 64 diseases in open-access papers, as found by Europe PMC text mining. Sharing a sentence is not in itself a finding about the gene and the disease. The quoted sentences say what the papers report.
Noonan syndrome (33 papers, 2012 to 2026). "Mutations in SHOC2, which is involved in Noonan-like syndrome, were identified in two cases, and SMARCAL1 mutations associated with Schimke immuno-osseous dysplasia were confirmed in two additional cases." (PMID 40959740, 2025). "Deleterious mutations in SHOC2 are known to cause Noonan syndrome, which is characterized by lentigines, a benign hyperplasia of melanocytes." (PMID 39337694, 2024). "During our study, patients with Noonan-like syndrome (SHOC2 gene mutation), mitochondrial pathology, and EXT2 gene variant showed distinctive treatment responses." (PMID 39529965, 2024). "For example, patients with Noonan syndrome (SHOC2 mutation) had a lower growth rate increase with rhIGF-1 treatment compared to other subjects with standard GH receptor gene deletions." (PMID 39529965, 2024). "Participant NE026 was diagnosed with Noonan-like syndrome with loose anagen hair caused by a heterozygous SHOC2 variant (c.4A > G, p.Ser2Gly)." (PMID 38028619, 2023). "Pathogenic variants in the RASopathy-causing SHOC2 gene have been suggested to cause Noonan syndrome-like with loose anagen hair (NS/LAH)." (PMID 36579329, 2022). "Another study found that the S2G mutation of Shoc2 causes Noonan-like syndrome by promoting aberrant protein N-myristoylation and results in Shoc2 plasma membrane targeting." (PMID 23805200, 2013). "Furthermore, single mutation of Shoc2 causes Noonan-like syndrome, a type of neuro-cardio-facial-cutaneous disorders, by enhancing ERK activation." (PMID 25514808, 2014). "It has been proposed that overexpression of the Shoc2 mutant with the S2G substitution (serine 2 is mutated to glycine), found in Noonan-like syndrome patients, results in N-myristoylation and targeting of this Shoc2 mutant to the plasma membrane, and enhances EGFR-dependent ERK1/2 activity." (PMID 22606262, 2012). "Noonan Syndrome is due to germline pathogenic variants involving genes such as PTPN11, SOS1, KRAS, NRAS, SHOC2, CBL and MAP2K1." (PMID 36982349, 2023). "Other rarer mutations, leading to the development of Noonan Syndrome, have been observed in the BRAF, SHOC2, and CBL genes." (PMID 36982349, 2023). "Secondary screening confirmed the enhanced sensitivity of RIT1-mutant cells to depletion of USP9X and AURKA along with the RAS pathway and Noonan syndrome genes SHOC2 and SOS1." (PMID 34373451, 2021). "A pioneering study of patients with Noonan-like syndrome revealed that several patients have de novo S2- > G substitutions in human leucine-rich repeat protein SHOC-2 (SHOC2) that result in the ex nihilo birth of a myristoylation motif." (PMID 26589632, 2015). "We describe pathogenic copy number variations in two individuals, a 24 Mb duplication of 12q24 containing PTPN11 resulted in apparent Noonan syndrome, while the 183 kb deletion of 10q25.2 including SHOC2 contributed to atypical Noonan-like syndrome." (PMID 24739123, 2014). "However, SHOC2 also plays vital roles in normal physiology; germline mutations in components of the SHOC2–PP1C regulatory axis cause Noonan-like syndromes with cardiac abnormalities, necessitating careful on-target toxicity evaluation." (PMID 41307844, 2025). "Indeed, gain-of-function SHOC2 mutations have been linked to RASopathies, a group of clinical pathologies associated with dysregulated RAS/MAPK signaling such as Noonan syndrome and patients with these syndromes are predisposed to certain cancers." (PMID 38753575, 2024). "In addition to the PTPN11 mutations in the RAS‐MAPK signaling pathway, including KRAS, SOS1, RAF1, SHOC2, NRAS, BRAF and CBL, can also cause Noonan syndrome." (PMID 37525886, 2023).
Noonan syndrome (continued). "In addition, we verified by exomeanalysis that the patient did not have any pathogenic variants in the genes associatedwith Noonan Syndrome and other rasopathies (PTPN11,SHOC2, KRAS, CBL,SOS1, RAF1, HRAS,NRAS, RASA1, SPRED1,BRAF, MAP2K1, MAP2K2, RIT1 andRRAS)." (PMID 27561113, 2016). "Noonan syndrome is a cluster of monogenic conditions involving several genes in the RAS-MAPK pathway (PTPN11, SOS1, SHOC2, MAP2K1/2 and KRAS in the included paper)." (PMID 36729042, 2023). "Finally, germline mutations affecting SHOC2 (suppressor of clear, C. elegans, homolog), a gene located in 10q25.2, usually result in Noonan syndrome-like phenotypes (OMIM#607721) and JMML, and a classic Noonan syndrome in a small proportion of affected individuals." (PMID 28955657, 2017). "In our study, patient 2 (deletion of SHOC2) had DORV, which was seldom reported in Noonan syndrome or Noonan-like syndrome." (PMID 24739123, 2014). "Our experimental model (Cos-LV1 cells) is reminiscent of the Noonan-like syndrome because Shoc2-S2G mutant was expressed in these cells in the absence of wild type Shoc2." (PMID 22606262, 2012).
RASopathies (22 papers, 2012 to 2025). "Rasopathy mutations of SHOC2, MRAS and PP1C map to subunit interfaces and enhance complex formation, driving RAF dimerization and MAPK flux." (PMID 35830882, 2022). "Rasopathy-associated mutations SHOC2(M173I) and Q269_H270delinsHY (Q269H/H270Y); MRAS G23V, T68I and Q71R; PP1Cα P50R (corresponding to PP1Cβ P49R); and non-rasopathy SHOC2 LOF mutations D175N and E457K all map to interaction sites." (PMID 35830882, 2022). "GOF mutations causing rasopathies have been reported on SHOC2, MRAS and PP1Cβ7–10,13,14,19,34,35." (PMID 35830882, 2022). "We reasoned that rasopathy-associated gain of function (GOF) mutations in SHOC2 and/or MRAS might stabilize the ternary complex and therefore facilitate structural analysis." (PMID 35830882, 2022). "The rasopathy GOF SHOC2(M173I) mutation boosted this activity." (PMID 35830882, 2022). "Moreover, several SHOC2 loss of function (LOF) mutants unrelated to rasopathy were identified through genetic screens that abolish RTK–RAS-activated phenotypes in Caenorhabditis elegans." (PMID 35830882, 2022). "A recurrent activating mutation at the very N-terminus of SHOC2 (Ser-2 to Gly) leads to N-myristoylation of SHOC2, confers continuous membrane association and consequently causes Mazzanti syndrome, a RASopathy characterised by features resembling Noonan syndrome." (PMID 34103645, 2021). "A total of 13 patients with RASopathy and SLE have been reported in the literature, five variants associated with SHOC2, two with KRAS, one with PTPN11 and five remained genetically undiagnosed." (PMID 40085019, 2025). "Our structural mapping of disease-relevant rasopathy mutations in SHOC2, MRAS and PP1C, as well as structure–function studies on specific SHOC2 GOF and LOF variants, establish a mechanistic basis for their function." (PMID 35830882, 2022). "We next showed that rasopathy-derived SHOC2 GOF mutant M173I results in a twofold increase in MRAS recruitment, which is reverted when the isoleucine is replaced by a glutamic acid." (PMID 35830882, 2022). "MRAS, SHOC2 and PP1C are mutated in rasopathies—developmental syndromes caused by aberrant MAPK pathway activation—and SHOC2 itself has emerged as potential target in receptor tyrosine kinase (RTK)–RAS-driven tumours." (PMID 35830882, 2022). "We find enrichment in RASopathy mutations for NF1, while RASA1 and SHOC2 have mainly cancer mutations." (PMID 24803665, 2014). "Furthermore, genetic analysis revealed variants in genes associated with other RASopathies in four patients: HRAS (one patient), SHOC2 (two patients), and PPPCB1 (one patient)." (PMID 37568403, 2023). "In addition to the role of SHOC2 in tumour settings, gain- and loss-of-function mutations in SHOC2, PP1C and MRAS have been identified in RASopathies with dysregulated MAPK signalling." (PMID 35768504, 2022). "This is might be the first report suggesting that haploinsufficiency of SHOC2 can result in a RASopathy-like phenotype." (PMID 24739123, 2014). "For example, RASopathies, such asNoonan syndrome, Neurofibromatosis 1 and Leopard syndrome, are a subtype ofdevelopmental diseases characterized by mutations in genes encoding for components ofthe Ras/MAPK pathway (NF1, PTPN1, SOS1, RAF1,KRAS, NRAS, SHOC2, CBL)." (PMID 29719609, 2018). "Similarly, the rasopathy-associated Q71R mutation in MRAS, which is expected to inhibit nucleotide hydrolysis and stabilize the active GTP-bound conformation, also resulted in an increase in affinity to the wild-type (WT) SHOC2 LRR domain (8×/3× binary/ternary)." (PMID 35830882, 2022). "For the RASopathy genes, no protein structures were available for RAF1, MAP2K2, or SHOC2 (9 total variants)." (PMID 25802880, 2015).
lung carcinoma (5 papers, 2019 to 2024). "Our recent study showed that in lung cancer cells, SHOC2 positively regulated the MAPK but negatively regulated the mTORC1 signals." (PMID 39871893, 2024). "Our previous study showed that SHOC2 also negatively regulated the mTORC1 signal by competing with mTOR for Raptor binding in lung cancer cells." (PMID 39871893, 2024). "Our recent study showed that SHOC2 is also a negative regulator of the mTORC1 signal in lung cancer cells." (PMID 39871893, 2024). "Recent studies indicate co-dependence signaling by SHOC2 signaling in either KRAS mutant or EGFR mutant lung cancer cells." (PMID 34102455, 2021). "Recent studies have also suggested that SHOC2 may hold prognostic value for patients with breast, thyroid, and lung cancers." (PMID 39871893, 2024). "Moreover, genetic inhibition of SHOC2 suppresses tumor development in autochthonous murine Kras-driven lung cancer models." (PMID 36966223, 2023). "Taken together, these observations show that concomitant genetic SHOC2 inhibition potentiates the cytotoxic properties of MEKi’s in a BIM-dependent manner and increases antitumor efficacy in lung cancer cell lines." (PMID 31182717, 2019). "Here we show that genetic inhibition of SHOC2 suppresses tumorigenic growth in a subset of KRAS-mutant NSCLC cell lines and prominently inhibits tumour development in autochthonous murine KRAS-driven lung cancer models." (PMID 31182717, 2019).
melanoma (5 papers, 2014 to 2023). A malignant, usually aggressive tumor composed of atypical, neoplastic melanocytes. "In malignant melanoma, SHOC2 mediates acquired resistance of tumor cells to Raf inhibitor Vemurafenib through continuous activation of N-RAS." (PMID 37166421, 2023). "Up-regulation of Shoc2 during human melanoma metastasis also resulted in the ERK phosphorylation." (PMID 30333251, 2018). "In this context, Shoc2 expression is able to modulate both ERK activation and resistance to apoptosis of B-RafV600E/N-RasQ61K melanoma cells in the presence Raf inhibitor." (PMID 25514808, 2014).
breast cancer (3 papers, 2021 to 2024). A primary or metastatic malignant neoplasm involving the breast. "SHOC2 has been reported to be a regulator of the Ras signaling pathway and is associated with poor prognosis among breast cancer patients." (PMID 34068918, 2021). "MiR-497-5p has the potential to make breast cancer cells more susceptible to the effects of paclitaxel by blocking both MALAT-1 and SHOC2." (PMID 38511067, 2024). "Further, SHOC2 knockdown inhibited the proliferation of breast cancer cells." (PMID 34504059, 2021).
Costello syndrome (2 papers, 2019 to 2023). "HRAS alterations were detected in only 2 out of 19 patients referred with a Costello syndrome suspicion, whereas pathogenic variants in RAF1 and SHOC2 were detected in 3 and 2, respectively." (PMID 37568403, 2023). "The remaining genes involved were RAF1 (three patients, all with Costello syndrome suspicion), RIT1 (two patients), BRAF (one patient), MAP2K1 (three patients), MAP2K2 (two patients), PTPN11 (two patients), SOS1 (one patient), and SHOC2 (three patients, two of them with Costello syndrome suspicion)." (PMID 37568403, 2023).
glial tumors (2 papers, 2007 to 2025). "Besides, because of the fact that structural/extracellular matrix-related genes or growth factor-related genes have an important role in glial tumors, it was recently suggested that SHOC2 function is essential for activation of MAPK pathway by growth factors." (PMID 17519038, 2007). "We focused on genes mediating selumetinib sensitivity as potentially druggable dependencies, and the top 2 conserved sensitivity hits were BRAF, a direct effector of Ras with established roles in glioma, and SHOC2, which has not been previously implicated in glioblastoma to our knowledge." (PMID 40985888, 2025).
Leopard syndrome (2 papers, 2011 to 2018). "Seven genes (PTPN11, SOS1,KRAS, RAF1, BRAF,SHOC2 and MEK1, alias MAP2K1) have beencausally related to NS and closely related conditions (including LEOPARDsyndrome) and clinically related disorders (e.g. neurofibromatosis type 1)." (PMID 21526175, 2011).